APAF1 (apoptotic peptidase activating factor 1)
Diseases named in the same sentence as APAF1 in open-access papers (continued):
Sharing a sentence is not in itself a finding about the gene and the disease.
lung carcinoma (15 papers, 2006 to 2024). "As miR-155 overexpression is observed in various malignancies including that of lung cancer, it has been found that miR-155 inhibition restores sensitivity of lung cancer to cisplatin via negative regulation of Apaf-1 expression." (PMID 34210046, 2021). "MiR-155 silencing enhances the sensitivity of A549 lung cancer cells to cisplatin by activating the initiator caspase-9 through apoptotic peptidase activating factor 1 (Apaf-1)." (PMID 32438598, 2020). "In the A549 lung cancer cell line, miR-155 modulates cellular apoptosis and DNA damage through an Apaf-1-mediated pathway." (PMID 33294082, 2020). "Apoptotic protease activating factor-1 (Apaf-1), the structural core of the apoptosome, was shown to be directly regulated by miR-300 in lung cancer cells." (PMID 32585857, 2020). "In their study, miR-155 was shown to modulate celluar poptosis and DNA damage via Apaf-1 regulated pathways to decrease the sensitivity of lung cancer cells to cisplatin." (PMID 31727002, 2019). "APAF1 was recently independently demonstrated as miR-221 target in lung cancer derived-cell lines, thereby giving support to our finding." (PMID 23630541, 2013). "Also it has been shown that miR-155 can downregulate the expression level of apoptotic protease activating factor 1 (Apaf-1), thereby inhibiting cell apoptosis induced by cisplatin in lung cancer cells." (PMID 28939896, 2017). "In lung cancer, PRRX1 knockdown inhibits the expression of Caspase 3, caspase 9, Apaf-1, and cytochrome C, leading to enhanced anti-apoptotic capacity and resistance to cisplatin in lung cancer cells." (PMID 32811812, 2020). "We demonstrated that inhibition of caspase-9 in lung cancer cells could not be attributed to abnormal expression of Apaf-1 and procaspase-9 or to genetic alterations in the procaspase-9 coding sequence analysed in NSCLC H460 cells." (PMID 16796750, 2006).
colorectal cancer (12 papers, 2011 to 2024). A primary or metastatic malignant neoplasm that affects the colon or rectum. "Mechanically, the gene of Apaf-1, which is associated with the mitochondrial apoptosis, was demonstrated to be the target of microRNA-27a in colorectal cancer stem cells." (PMID 28423356, 2017). "In humans, downregulation of APAF1 is evident in colorectal cancer and hepatocellular carcinoma cells given transcriptional regulation by miR-23a and Histone Deacetylases 1–3." (PMID 33175867, 2020). "Mechanically, our results demonstrated that miR-27a antioligonucleotides increased the expression of Apaf-1 in TRAIL-treated colorectal cancer stem cells." (PMID 28423356, 2017). "Here, we provide evidences that miR-27a antioligonucleotides sensitize colorectal cancer stem cells to TRAIL by promoting the formation of Apaf-1-caspase-9 complex." (PMID 28423356, 2017). "Moreover, APAF1 positively regulated the 5-FU-induced mitochondria-mediated apoptosis in colorectal cancer cells." (PMID 27588397, 2016). "Reduced expression of Apaf-1 in colorectal carcinoma correlates with high-grade phenotype." (PMID 21342584, 2011). "In the TMA-validated hypothesis, “Reduced expression of Apaf-1 in colorectal cancer correlates with high-grade phenotype”, for example, ‘colorectal cancer’ is biological condition, and “reduced Apaf-1 expression” and “high-grade phenotype” are entities (B and C)." (PMID 21342584, 2011). "Knockdown of microRNA-27a increased the expression level of Apaf-1, thus enhancing the formation of Apaf-1-caspase-9 complex and subsequently promoting the TRAIL-induced apoptosis in colorectal cancer stem cells." (PMID 28423356, 2017).
gastric cancer (11 papers, 2011 to 2026). A primary or metastatic malignant neoplasm involving the stomach. "It has been shown that there was a significant association between the levels of APAF1 methylation, tumor stage, and grade in blood samples of a subpopulation of Iranian gastric cancer patients." (PMID 33883026, 2021). "In gastric cancer, Apaf-1 expression is associated with high grade malignancy." (PMID 21342584, 2011). "Then ABL can bind to the WD1/WD2 domain of APAF1, competitively blocking the interaction between cytochrome c and APAF1, ultimately blocking gastric cancer cell apoptosis and potentially contributing to multidrug resistance." (PMID 41517663, 2026). "Chinese gastric cancer patients had also significant higher ratio of APAF1 methylation in their tumor tissues compared with normal margins." (PMID 33883026, 2021). "In both studies on gastric cancer cell lines, cytochrome C release and Apoptotic protease activating factor 1 (Apaf-1) upregulation were observed." (PMID 33167519, 2020). "In addition, ABL interacts with APAF1 to block apoptosome assembly and caspase‐9/3 activation, leading to resistance to cell death in gastric cancer cells." (PMID 35975461, 2022). "HSP-treated gastric cancer inhibited cell proliferation by inducing apoptosis by increasing Bax/Bcl-2 ratio, cyt-c,caspase-3, caspase-9, AIF, and Apaf-1 via a mitochondrial-dependent pathway in vitro and xenograft tumours at a dose-dependent manner." (PMID 35128104, 2022). "Earlier reports suggested that apoptotic genes like APAF-1, Bcl-2, BAX, and Bcl-2 family were found to be up-regulated in gastric cancer tissues." (PMID 32993565, 2020). "In gastric cancer, ABL is involved in the antiapoptotic pathway, by interaction with APAF1 and inhibition of APAF1 recognition by cytochrome c; targeting ABL may restore the apoptosome and caspase activation leading to cell death." (PMID 39280246, 2024).
hepatocellular carcinoma (10 papers, 2011 to 2024). A malignant tumor that arises from hepatocytes. "mir-142 and APAF1 as target gene are proposed as a promising non-invasive diagnostic biomarker of hepatocellular carcinoma, which have been detected by MSRFR for kidney tissue." (PMID 36230862, 2022). "Proapoptotic APAF-1 is upregulated by HDACi in hepatocellular carcinomas." (PMID 33167494, 2020). "In hepatocellular carcinomas, proapoptotic APAF1 is upregulated by HDACi." (PMID 31234549, 2019). "UTP6 Small Subunit Processome Component (UTP6), or Hepatocellular carcinoma antigen 66 (HCA66), is a positive regulator of Apaf-1-dependent apoptosis." (PMID 38448973, 2024).
laryngeal carcinoma (10 papers, 2016 to 2025). Carcinoma that arises from the laryngeal epithelium. "As a noncoding RNA, miRNA plays an important role in laryngeal cancer and inhibits norepinephrine-induced cardiomyocyte apoptosis by regulating the expression of Apaf-1." (PMID 40426921, 2025). "Further, another study pointed out that MEG3 regulated the expression of apoptotic peptidase activating factor 1 (APAF-1) by competitively binding to miR-23a in laryngeal cancer." (PMID 36544907, 2022). "The involvement of the miR-23a-3p/APAF1 axis has been reported in several solid cancers, including colorectal, pancreatic and laryngeal carcinomas and glioma." (PMID 34283087, 2021). "LncRNA MEG3 blocks cell proliferation and induces cell apoptosis in laryngeal cancer through regulating miR-23a/APAF-1 axis." (PMID 32420340, 2020). "Taken together, these results support the conclusion that MEG3, miR‐23a and APAF‐1 form a ceRNA regulatory network in the progression of laryngeal cancer." (PMID 31328388, 2019). "Similarly, MEG3 inhibits laryngeal cancer cell proliferation and induces cell apoptosis by regulating APAF-1." (PMID 38281945, 2024). "Furthermore, MEG3 acts as a ceRNA to regulate APAF‐1 expression via competitively binding to miR‐23a, thereby regulating the progression of laryngeal cancer." (PMID 31328388, 2019). "Furthermore, MEG3 may act as a ceRNA to regulate APAF‐1 expression by competitive binding to miR‐23a, thereby regulating the progression of laryngeal cancer." (PMID 31328388, 2019). "We conclude that demethylated SP1 sites in CG-rich region of miR-23a-27a-24-2 cluster promoter result in the cluster overexpression, leading to proliferation promotion and apoptosis inhibition probably via targeting the related targets such as APAF-1 and PLK2 in laryngeal cancer cells." (PMID 27099864, 2016). "First, although we have already demonstrated that the activations of APAF‐1 and its downstream caspases induced by MEG3 were rescued by miR‐23a, it is still not known whether the phenotype in laryngeal carcinoma induced by MEG3 was rescued by miR‐23a." (PMID 31328388, 2019).
colon carcinoma (9 papers, 2014 to 2025). "Similarly, the development of resistance to death receptor- and drug-induced apoptosis in colon carcinoma was associated with downregulation of Apaf-1." (PMID 27863378, 2016). "This contributed to the chemoresistance of the colon cancer cells to the 5-Fu, as the increased expression of the miR-23a can target the APAF-1 to reduce the cell apoptosis." (PMID 30577536, 2018). "Induction of pro-apoptotic APAF1, BAK, BIM, and BMF, and loss of anti-apoptotic BCLXL occurred within 12 h of MSP treatment, in both HCT116 and HT29 colon cancer cell lines." (PMID 25321483, 2014). "In summary, both TSGs ARHGEF12 and APAF1 expression were downregulated in colon cancer and could be reactivated by CUR, and upregulated ARHGEF12 and APAF1 may be associated with favorable prognosis of patients." (PMID 37731740, 2023). "When administered in combination with 5-fluorouracil, ginsenoside Rg3 can significantly increase the apoptosis rate in colon cancer (SW620 and LoVo) cells through the activation of the Apaf1/Caspase-9/Caspase-3 pathway." (PMID 40490812, 2025). "Among them, ARHGEF12 and APAF1 genes, which were most significantly upregulated by CUR, were preferentially selected as candidate targets for CUR in colon cancer cells." (PMID 37731740, 2023). "Minoo's study of 399 CRCs showed that TOPK could be a marker of tumor in colon cancer in combination with CDX2, CD44v6, CD44s, nuclear ß-catenin, pERK, APAF-1, E-cadherin, p21, and bcl2." (PMID 25881543, 2015). "Additionally, bortezomib and PCC have been found to induce apoptosis in colon cancer cell lines by upregulating TRAIL-induced receptors (TNFRS10 A/B), and bortezomib can decrease the growth of cancerous cells by restoring Apaf-1 and increasing the caspase-3 activity." (PMID 38339421, 2024). "Considering that CUR can significantly reactivate TSGs ARHGEF12 and APAF1, to further investigate whether upregulated ARHGEF12 and APAF1 expression in colon cancer correlates with patient prognosis, we analyzed colon cancer subtypes using Kaplan-Meier survival curves." (PMID 37731740, 2023).
glioma (8 papers, 2002 to 2023). A benign or malignant brain and spinal cord tumor that arises from glial cells (astrocytes, oligodendrocytes, ependymal cells). "Multiple molecular aberrations contribute to TRAlL-resistance of glioma, such as lower expression of caspase-8, overexpression of c-FLIP, Bcl-2 and Bcl-xL or loss or structural alterations of TRAIL-R1, TRAIL-R2, Apaf-1, Smac and Bid." (PMID 37158962, 2023). "Overexpression of APAF1 induced apoptosis in U-373MG human glioma cells." (PMID 36142793, 2022). "In addition, we found that in glioma tissues from the TCGA database, SAA1 levels were associated with a range of anti-apoptotic genes (Bcl-xl, BFL1, MCL1, BIRC5, and Fas) and pro-apoptotic genes (Bim, Bid, CASP9 and Apaf1)." (PMID 33854635, 2021). "In addition to the well-known and highly recurrent events, GTS defines and ranks many previously unrecognized CNAs, uncovers frequent codeletion of two related CKI genes, CDKN2C and CDKN2A, in human cancers, and implicates APAF1 and FBXW7 in glioma pathogenesis." (PMID 18394558, 2008).
leukemia (8 papers, 2004 to 2022). A malignant (clonal) hematologic disorder, involving hematopoietic stem cells and characterized by the presence of primitive or atypical myeloid or lymphoid cells in the bone marrow and the blood. "Blockage with HSP90-specific inhibitor geldanamycin (GA) also diminishes the association of HSP90 with APAF-1 or BCL-2 in leukemia cells, leading to apoptosis." (PMID 36139353, 2022). "Apaf-1 mediated, caspase-dependent apoptosis promoted by Az in leukemia cells should lead to activation of proteolysis of procaspase-9 to produce caspase-938." (PMID 28615625, 2017). "HSP90 promotes the survival of leukemia cells by binding to APAF-1 and BCL-2." (PMID 36139353, 2022). "APAF1 is inactivated by DNA methylation in several cancers and leukemia." (PMID 31321477, 2019). "Some of these AM genes are known to be dysregulated in leukaemia: up regulation of BIRC3 and down regulation of APAF1, CIDEB, FAS, TNFRSF25, TNFSF10 were previously identified by our group as specific alterations of AM genes in leukemic cells." (PMID 20642818, 2010).
bladder cancer (7 papers, 2013 to 2022). "Circular RNA Cdr1as sensitizes bladder cancer to CDDP by upregulating APAF1 expression through miR-1270 inhibition." (PMID 33874956, 2021). "Another study showed that circCdr1as sensitizes bladder cancer cells to CDDP by restoring the expression of APAF1, which is decreased by miR-1270." (PMID 32758239, 2020). "In this study, we explored the effect of circRNA Cdr1as on the cisplatin chemosensitivity of bladder cancer and demonstrate the related regulatory mechanism, that is, the novel Cdr1as/miR‐1270/APAF1 axis." (PMID 31131537, 2019). "The same results were found in cells overexpressing miR‐1270, which suggests that miR‐1270 regulates cisplatin chemosensitivity in bladder cancer by targeting APAF1." (PMID 31131537, 2019). "In the present study, we investigated the relationship between Cdr1as and the sensitivity of bladder cancer to cisplatin and explore the potential miRNA and downstream target gene APAF1 mechanistically." (PMID 31131537, 2019). "Based on our previous study and the present findings, we conclude that Cdr1as can adsorb miR‐1270 in bladder cancer, restore its suppressed APAF1 expression level, induce apoptosis, and increase cisplatin chemosensitivity." (PMID 31131537, 2019). "The expression level of apoptotic protease‐activating factor 1 (APAF1) in bladder cancer cells was identified via western blot." (PMID 31131537, 2019). "The cell apoptosis rates and cisplatin chemosensitivity of bladder cancer T24 and EJ cells were also significantly increased by knocking down APAF1." (PMID 31131537, 2019). "Targeting the Cdr1as/miR‐1270/APAF1 axis presents a new strategy to enhance the cisplatin chemosensitivity of bladder cancer patients." (PMID 31131537, 2019). "Our study verified that Cdr1as exerts a cisplatin‐chemosensitization effect on bladder cancer cells through the Cdr1as/miR‐1270/APAF1 axis." (PMID 31131537, 2019). "Similarly, “circRNA Cdr1as” induced apoptosis and increased the cisplatin chemosensitivity of bladder cancer cells both in vitro and in vivo by upregulating “APAF1” expression through miR-1270 inhibition." (PMID 36230649, 2022). "APAF1 silencing decreased the sensitivity of bladder cancer cells to CDDP." (PMID 32758239, 2020). "Relationship between APAF1 expression and clinicopathological features of bladder cancer patients." (PMID 31131537, 2019). "Silencing of APAF1 reduced the sensitivity of bladder cancer cells to cisplatin chemotherapy." (PMID 31131537, 2019). "Studies have indicated that DAC may be able to restore the function of the Apaf-1 gene in acute myeloid leukemia and induce apoptosis of bladder cancer cells by reversing the unmethylated status of the DAPK promoter." (PMID 23946818, 2013). "To investigate the effects of APAF1 on bladder cancer cells, we transfected si APAF1 or si‐CTL into T24 and EJ cells and subsequently detected protein levels of APAF1 by western blot." (PMID 31131537, 2019).
lymphoma (7 papers, 2010 to 2022). A malignant (clonal) proliferation of B- lymphocytes or T- lymphocytes which involves the lymph nodes, bone marrow and/or extranodal sites. "Caspase-9 deficiency and Apaf-1 deficiency were also incorporated into lymphoma model." (PMID 20145726, 2010). "Here we set out to investigate the clinical relevance of Apaf-1 mislocalization in primary cells derived from patients with lymphomas, and to establish a correlation between Apaf-1 mislocalization and apoptosis sensitivity in an ex vivo setting." (PMID 27863378, 2016). "Next, we undertook expression profiling to identify specific gene signatures and/or gene marker(s) differentially expressed in lymphomas with membrane localized Apaf-1." (PMID 27863378, 2016). "While the overall expression of Apaf-1 did not change in the clinical lymphomas we examined, the sub-cellular localization was significantly altered such that the protein was sequestered in lipid raft domains of the plasma membrane instead of being expressed in the cytosol." (PMID 27863378, 2016).
non-small cell lung carcinoma (6 papers, 2006 to 2024). A group of at least three distinct histological types of lung cancer, including non-small cell squamous cell carcinoma, adenocarcinoma, and large cell carcinoma. "In non-small-cell lung cancer cells, melittin has been shown to induce apoptosis by increasing caspase-3 protein expression and Apaf-1 mRNA levels." (PMID 39519238, 2024). "The imbalance between pro- and anti-apoptotic factors may lead to accumulation of transforming mutations and resistance or decreased sensitivity to anticancer treatment, as shown for APAF-1 inactivation in human leukaemic cells or DAPK-1 inactivation in non-small cell lung cancer cells." (PMID 17133271, 2006).